IL17A (interleukin 17A)
Diseases named in the same sentence as IL17A in open-access papers (continued):
Sharing a sentence is not in itself a finding about the gene and the disease.
tendinopathy (continued). "Recent clinical evidence suggests blockade of interleukin 17A (IL-17A) for tendinopathy therapy." (PMID 39988349, 2025). "However, the role of the IL-17A pathway and its contribution to tendinopathy remains largely understudied." (PMID 35004653, 2021). "Furthermore, we have recently shown the translational potential of IL-17A in the soft tissue musculoskeletal condition, tendinopathy." (PMID 34544860, 2021). "Our study provides evidence that IL-17A could operate as a cytokine modulator of early tendinopathy." (PMID 27263531, 2016). "Our data demonstrate in human tendinopathy that IL-17A is upregulated and thereafter capable of inducing other inflammatory cytokines that may ultimately disturb the balance between reparative and degenerative processes in the extracellular matrix." (PMID 27263531, 2016). "Herein we demonstrate that IL-17A is present in early tendinopathy biopsies and thereafter in mechanistic studies demonstrate that IL-17 likely contributes to regulation of inflammatory and apoptotic pathways in tendon cells, associated with a change in collagen matrix synthesis." (PMID 27263531, 2016). "Based on our previous observations concerning cell death in early tendinopathy, we utilised limited proteomic profiling to assess which apoptotic mediators may be regulated by IL-17A." (PMID 27263531, 2016). "Based on these observations and the plausible biological profile exhibited by IL-17A, we hypothesized that IL-17A may play a role in tendinopathy." (PMID 27263531, 2016). "The IL-17A receptor heterodimer subunits IL17RA and IL17RC were constitutively expressed with medium abundance; however, IL17RA and IL17RC receptor expression was not linked to the upregulated expression of IL17A and was not significantly altered in tendinopathy." (PMID 39988349, 2025). "IL-17A blockade may, therefore, be a potential therapy in early-stage tendinopathy." (PMID 39988349, 2025). "However, IL17RA and IL17RC receptor expression is not linked to IL17A expression and is not regulated in tendinopathy." (PMID 39988349, 2025). "However, the IL-17A pathway remains largely underexplored in tendinopathy." (PMID 35004653, 2021). "Based on these observations, we hypothesized that IL-17A signaling may be involved in mediating the inflammatory and tissue remodeling changes present in frozen shoulder in a similar manner to that which is involved in tendinopathy." (PMID 34544860, 2021). "On the basis of these results we propose IL-17A as an inflammatory regulator in tendon remodeling - better understanding of the pathological cascade that it induces should lead to the development of cell targeted treatment modalities for early human tendinopathy." (PMID 27263531, 2016). "Thus further mechanistic work in diseased tenocytes may be required to determine the hierarchical and discrete kinetic roles of IL-17A mediated apoptosis in early versus late tendinopathy." (PMID 27263531, 2016). "The majority of IL-17A+ cells double-stained with MCT, suggesting that mast cells represent a lineage in which IL-17A protein expression is enriched in human tendinopathy." (PMID 27263531, 2016). "In addition, here, we demonstrate the differential expression of IL17A in contrast to the other IL-17 family members, IL17B, IL17C, IL17D and IL17E in early-stage tendinopathy compared with late-stage tendinopathy and healthy tendon." (PMID 39988349, 2025). "In contrast, in human late-stage tendinopathy, we have not observed differential expression of IL17A and the other IL-17 family members." (PMID 39988349, 2025). "Increased expression of IL-17A was detected in ‘early tendinopathy’ compared to both matched samples and non-matched control samples (p < 0.01) by RT-PCR and immunostaining." (PMID 27263531, 2016). "The IL-17A-induced expression of downstream inflammatory effectors IL-6, CXCL1 and MMP3 was completely inhibited by secukinumab, suggesting that IL-17A alone and in concert with TNF-α may promote inflammation in tendinopathy." (PMID 39988349, 2025).
tendinopathy (continued). "However, in combination with TNF-α, all three IL-17 cytokines induce similar levels of IL6 and MMP3 mRNA expression, which could make not only IL-17A, but also IL-17F and IL-17AF interesting treatment targets in tendinopathy." (PMID 35004653, 2021).
chronic kidney disease (15 papers, 2016 to 2025). Impairment of the renal function secondary to chronic kidney damage persisting for three or more months. "The other report indicates that IL-17A is involved in acute and chronic kidney disease, the renal injury is ameliorated in IL-17A deficient DKD mice compared with wild-type mice." (PMID 36646672, 2023). "Another study revealed that adropin treatment in chronic renal failure rat models also decreased renal damage markers such as NGAL (neutrophil gelatinase-associated lipocalin), TIMP-1, IL-17A, IL-33, MMP-2, and MMP-3, while increasing MMP-13 levels." (PMID 39906123, 2025). "Moreover, the transcript level of IL-17A was increased in the blood of type 2 DM patients during all five stages of chronic kidney disease." (PMID 37372951, 2023). "Additionally, circulating IL-17A levels were increased in patients with chronic kidney disease." (PMID 33391465, 2021). "In rats with adenine-induced chronic renal failure, adropin treatment was shown to reduce the expression of several pro-inflammatory cytokines, including G-CSF (granulocyte colony-stimulating factor), IFN-γ, IL-4, IL-5, IL-10, IL-12, IL-17A, and GRO-α (growth-related oncogene-alpha)." (PMID 39906123, 2025).
Giardia infection (15 papers, 2017 to 2024). "Asking if the moderate difference in susceptibility to Giardia infection correlated with the activity of Th17 cells, we surveyed RORγt and IL-17A expression by CD4+ T cells in BALB/c and C57BL/6 mice at steady state and two weeks post G. muris infection." (PMID 31889073, 2019). "The researchers used flow cytometry to detect the immune response to Giardia infection, and they found an upregulation of IL-17A and TNF production by CD4+ CD197− CD45RA− T cells." (PMID 36679941, 2022). "First we studied cytokines that earlier have been shown to be up-regulated during Giardia infections in mice, i.e. IL-1, IL-2, IL-4, IL-5, IL-9, IL-10, IL-12, IL-17a, IL-17c, IFN-γ, TGF-β, and TNF-α." (PMID 34335577, 2021). "In human giardiasis, the IL-17A revealed an important protective immune response against Giardia." (PMID 36679941, 2022). "The most important downstream effectors of the IL-17A response, that have been shown to play a critical role in the clearance of a Giardia infection, are the activation of the complement system by mannose-binding lectin 2 (MBL2) and the production and secretion of parasite-specific IgA’s4,6,7." (PMID 34011991, 2021). "As the degree of SFB colonization is regulated by IL-17A and IgA49,50 it will be interesting to assess if Giardia infection further stunts Th17 and IgA responses directed against gut microbes in BALB/c mice, permitting the expansion of species colonizing the epithelial layer." (PMID 31889073, 2019). "However, insights in the precise protective effector mechanism(s) triggered by IL-17A following a Giardia infection are still scarce." (PMID 28819174, 2017).
HIV-1 infection (15 papers, 2015 to 2025). The type species of lentivirus and the etiologic agent of acquired immunodeficiency syndrome (AIDS). "Pulmonary infection with C. neoformans strain H99c increased the pulmonary IL-17 (commonly known as IL-17A) production, and the IL-17 level of cerebrospinal fluids (CSF) in HIV-1 infection-associated CM is significantly higher than that in tuberculous meningitis (TBM)." (PMID 35720334, 2022). "At day 3 postinfection, we observed partial inhibition of the RORC2 mRNA expression in all the tested donors, which resulted in a lower IL-17A production from the treated cells relative to controls and a small but significant reduction of HIV-1 infection as measured by the quantity of proviral DNA." (PMID 34819367, 2021).
hyperlipidemia (15 papers, 2013 to 2026). "A cross-talk between IL-17A and lipids was shown in a study, where hyperlipidemia induced IL-17A production and the subsequent activation of human aortic endothelial cells." (PMID 36983201, 2023). "The results showed that smoking affects the frequency shift of Th17 and γδ+ T cells and IL-17A levels, while hyperlipidemia only affected the frequency shift of γδ+ T cells in IS patients." (PMID 24991091, 2014).
knee osteoarthritis (15 papers, 2016 to 2026). "Our research suggests that IL-17A(rs2275913) and IL-17F(rs763780) gene polymorphisms are a risk factor for knee osteoarthritis (p < 0.05)." (PMID 31842922, 2019). "Polymorphisms of IL-17A/F gene were the recognized candidate genes associated with knee osteoarthritis risk although the results were conflicting." (PMID 31842922, 2019). "The most important finding was that polymorphisms of IL-17A(rs2275913) and IL-17F(rs763780) gene associate with the risk of knee osteoarthritis in different ethnics." (PMID 31842922, 2019). "By a pilot study with small population, IL-17 polymorphisms (IL-17A rs2275913 and IL-17F rs763780) showed a more potential risk factor in knee osteoarthritis (OA) in our recruited subjects." (PMID 30658595, 2019). "The aim of this study was to determine whether IL-17A(rs2275913) and IL-17F(rs763780) polymorphisms confer susceptibility to knee osteoarthritis." (PMID 31842922, 2019). "Bafrani found that IL-17A(rs2275913) gene may be a protective factor against knee osteoarthritis while the IL-17F(rs763780) gene may be a risk factor for knee osteoarthritis." (PMID 31842922, 2019). "The correlation between the polymorphisms of IL-17A and IL-17F and the risk of knee osteoarthritis among the Chinese population has not been reported." (PMID 30658595, 2019). "PRP treatment for knee osteoarthritis effectively lowers the concentrations of inflammatory factors IL-6, IL-1β, TNF α, IL-17A, and IL-10, significantly alleviating knee joint pain and enhancing joint functionality." (PMID 37869166, 2023).
Miscarriage (15 papers, 2016 to 2025). A pregnancy that ends at a stage in which the fetus is incapable of surviving on its own, defined as the spontaneous loss of a fetus before the 22th week of pregnancy. "The serum of miscarriage patients has been shown to contain significantly higher levels of specific inflammatory cytokines (IL-2, IL-17A, IL-17F, TNF-α, and IFN-γ)." (PMID 39203483, 2024). "Our study is in accordance with those reporting increased levels of IL-17A in pregnancies complicated by miscarriage, preterm birth, and PE compared to normotensive pregnancies implicating the role of this cytokine in the pathophysiology of PE." (PMID 32550763, 2020). "Here we report that IL-2, IL-17A, IL-17F, TNF-α, and IFN-γ are significantly increased in serum of miscarriage patients." (PMID 33731680, 2021). "The current study also found that serum levels of IL-2, IL-17A, IL-17F, TNF-α, and IFN-γ were markedly increased in miscarriage patients compared to the controls." (PMID 33731680, 2021). "Multiplex analysis revealed markedly increased serum levels of IL-2, IL-17A, IL-17F, tumor necrosis factor-α (TNF-α), and IFN-γ in miscarriage patients than those in the controls." (PMID 33731680, 2021). "Compared with the control group, the IL-2, IL-17A, IL-17, TNF-α, and IFN-γ levels of serum were increased significantly in the miscarriage group." (PMID 34966824, 2021).
spondylitis (15 papers, 2017 to 2024). The inflammation of a vertebra. "In our study dual anti-TNF and anti-IL-17A therapy resulted in significant reduction of spondylitis and swelling at the level of the peripheral joints." (PMID 35055042, 2022). "Both single therapies as well as TNF and IL-17A dual blockade therapy reduced clinical spondylitis and peripheral arthritis effectively and similarly." (PMID 35055042, 2022). "Expression of a MAIT cell activation marker CD69 on IL-17A+ MAIT cells was correlated with the Ankylosing Spondylitis Disease Activity Score (ASDAS) in patients with AS." (PMID 35222393, 2022).
bullous pemphigoid (14 papers, 2013 to 2025). Bullous pemphigoid (BP) is the most common form of autoimmune bullous dermatosis. "It has already been proven that the levels of some proinflammatory cytokines, such as interleukin (IL)-1a, IL-6 IL-8, IL-17a, TNF-alpha, and IFN-c, were higher in the aqueous humor of eyes with bullous keratopathy and a low density of ECs." (PMID 36968840, 2023).
endotoxemia (14 papers, 2012 to 2022). "Together, these results indicate that IL-17A is involved in LPS-induced memory impairment and suggest a use for IL-17A Abs in limiting the adverse cognitive outcomes caused by endotoxemia." (PMID 26373740, 2015). "Therefore, a therapeutic approach targeting IL-17A may help to diminish the metabolic burden of endotoxemia caused by defective intestinal barrier functions." (PMID 31727909, 2019). "We next analyzed mRNA expression levels of neutrophil chemoattractants upon neutralizing IL-17A or depleting γδ T cells in endotoxemia." (PMID 33981320, 2021). "IL‐18 originally named as “interferon‐c‐inducing factor,” and IL‐18 potentiated mortality in both neonatal sepsis and endotoxemia through the induction of IL‐17A." (PMID 33378581, 2021). "In GFAP/IL-17A mice, LPS-induced endotoxemia led to a more pronounced microglial activation with expansion of a distinct CD45high/CD11b+ population and increased induction of proinflammatory cytokines compared with controls." (PMID 23468966, 2013). "Anti-IL-17A may represent a new therapeutic strategy for the treatment of endotoxemia-induced neuroinflammation and cognitive dysfunction in aged rats." (PMID 33182582, 2020). "Anti-IL-17A may represent a new therapeutic strategy for the treatment of endotoxemia-induced neuroinflammation and cognitive dysfunction." (PMID 26373740, 2015). "Anti-IL-17A may be a new therapeutic strategy for the treatment of endotoxemia-induced neuroinflammation and cognitive dysfunction." (PMID 26373740, 2015). "We demonstrated that IL-17A was elevated in HFD-treated small intestine, and the neutralization of IL-17A improved the indomethacin-induced damage, intestinal permeability, and characteristics of endotoxemia." (PMID 31727909, 2019).
herpes zoster (14 papers, 2016 to 2025). A common dermal and neurologic disorder caused by reactivation of the varicella-zoster virus that has remained dormant within dorsal root ganglia, often for decades, after the patient's initial exposure to the virus in the form of varicella (chickenpox). "However, FAERS data identified higher-than-expected herpes zoster signals, likely reflecting IL-17A’s critical role in controlling varicella-zoster virus reactivation." (PMID 40408459, 2025).
kidney (14 papers, 2013 to 2024). "In particularly, it has also been reported that both functional and histological kidney injuries were dependent on the production of the cytokine IL17A, and that both were attenuated by depleting IL17A." (PMID 37074502, 2023). "Studies indicated that the occurrence of prostatitis may be related to inflammation and the immune reaction, and IL17A- and IFN-γ-expressing cells induce chronic pelvic pain." (PMID 38256890, 2023). "The transcription levels of IL-17F (a subfamily of IL-17), IL-23 (an inducing factor of IL-17A), and Foxp3 (a marker for regulatory T cells) were altered in the kidneys of both adenine-induced kidney injury groups; the levels were comparable between SPF and GF groups." (PMID 32859011, 2020).
meningitis (14 papers, 2014 to 2022). A disorder characterized by acute inflammation of the meninges of the brain and/or spinal cord. "Our other study found that IL-17A might mediate E. coli clearance via increasing antimicrobial peptides, which require further investigation to comprehensively interpret the function of IL-17A throughout E. coli meningitis pathogenesis." (PMID 35221923, 2022). "Elucidating mechanisms of the IL-17A-induced BBB disruption may provide an accurate and effective target for preventing BBB breakdown in meningitis." (PMID 35221923, 2022). "In meningitis pathophysiology, BBB disruption is an obligatory outcome, accompanied by acute inflammatory responses, with the release of multiple inflammatory factors such as TNF-α, IL-1β, IL-6, IL-17A, MCP1, and GRO-α." (PMID 31783671, 2019).